OR11H6 (olfactory receptor family 11 subfamily H member 6)
Description:
Odorant receptor.
Tractability: Antibody: its Gene Ontology location is reachable by antibodies, with high confidence; UniProt places it where antibodies can reach, with medium confidence; UniProt predicts a signal peptide or a membrane-spanning region.
Gene: Protein-coding gene on chromosome 14 (20,223,710 to 20,224,702, forward strand). Ensembl gene ENSG00000176219.
Subcellular location: Cell membrane
Pathways (Reactome):
Sensory Perception: Expression and translocation of olfactory receptors; Olfactory Signaling Pathway
Gene Ontology:
Molecular function: G protein-coupled receptor activity; olfactory receptor activity
Biological process: detection of chemical stimulus involved in sensory perception of smell; G protein-coupled receptor signaling pathway
Cellular component: plasma membrane; membrane
Genetic constraint (gnomAD): Loss-of-function variants: 9 observed, 17.54 expected, observed/expected ratio (o/e) 0.51, 90% interval 0.31 to 0.9. The upper end of that interval is the gene's LOEUF score, 0.9, which puts it in group 3 of 6, group 1 being the genes least tolerant of losing a copy. Missense variants: 377 observed, 402.64 expected, observed/expected ratio (o/e) 0.94, 90% interval 0.86 to 1.02. Synonymous variants: 134 observed, 153.39 expected, observed/expected ratio (o/e) 0.87, 90% interval 0.76 to 1.01.
Homologues: Orthologues: chimpanzee OR11H6 (99% identical), dog OR11H6 (87% identical), rabbit OR11H6 (84% identical), pig OR11H6 (83% identical), mouse Or11h6 (82% identical), rat Or11h6 (81% identical). Paralogues in human: OR11H4 (64% identical), OR11H12 (61% identical), OR11H2 (60% identical), OR11H1 (60% identical), OR11H7 (59% identical), OR11G2 (57% identical), OR11A1 (41% identical), OR9G1 (40% identical), OR10X1 (37% identical), OR9A1P (36% identical), OR9A4 (35% identical), OR9A2 (35% identical), and 21 more.
Diseases named in the same sentence as OR11H6 in open-access papers:
OR11H6 is named in the same sentence as 1 disease in open-access papers, as found by Europe PMC text mining. Sharing a sentence is not in itself a finding about the gene and the disease. The quoted sentences say what the papers report.
breast carcinoma (1 paper, 2024). "According to information from the KEGG database, we have discovered that in breast cancer, olfactory receptors such as OR11H6, OR1J4, OR4N5, and OR11G2O are associated with the olfactory transduction pathway." (PMID 38254021, 2024).